RELN (reelin)
Diseases named in the same sentence as RELN in open-access papers (continued):
Sharing a sentence is not in itself a finding about the gene and the disease.
Cerebral ischemia (2 papers, 2020 to 2022). Restriction of arterial blood supply to the brain associated with insufficient oxygenation to support the metabolic requirements of the tissue. "In support of this claim, the suppression of Reelin increases vulnerability after cerebral ischemia in mouse models." (PMID 35111956, 2022). "Our findings that the number of Reelin-positive cells decrease in the hippocampus after CCI are consistent with a previous study that showed decreased Reelin protein levels after cerebral ischemia by Western blot analysis." (PMID 32610618, 2020). "Likewise, it was suggested that Reelin can reduce pathologies related to cerebral ischemia–reperfusion injury." (PMID 35111956, 2022).
Cortical Dysplasia (2 papers, 2010 to 2019). "Further, ectopic Reelin has been reported to contribute to cortical dysplasia in another mouse model of PI3K pathway overactivation." (PMID 31094678, 2019). "In our model of cortical dysplasia, reelin restores the radial glial scaffold as well as glia-guided migration; NRG1, however, had a more limited effect since radial glia were realigned, but neuronal migration was not improved." (PMID 21060844, 2010).
Creutzfeldt-Jakob disease (2 papers, 2012 to 2020). "In neurodegenerative disorders such as Alzheimer's and Creutzfeldt-Jakob diseases, it was found that the glycosylation pattern of several glycoproteins, such as reelin, or acetylcholinesterase, is associated with disease pathogenesis." (PMID 22666317, 2012).
embryonal carcinoma (2 papers, 2012 to 2019). A non-seminomatous malignant germ cell tumor characterized by the presence of large germ cells with abundant cytoplasm resembling epithelial cells, geographic necrosis, high mitotic activity, and pseudoglandular and pseudopapillary structures formation. "To screen for Reelin proteases, we took advantage of the observation that P19 mouse embryonic carcinoma cells produce and secrete Reelin, but only upon retinoic acid-induced differentiation into neurons, they start to cleave the protein." (PMID 23082219, 2012). "However, the ExomeSeq data from patient 4 identified a single, shared missense mutation in the RELN gene between GCNIS and embryonal carcinoma." (PMID 30837548, 2019).
hypothyroidism (2 papers, 2021 to 2022). Abnormally low levels of thyroid hormone. "In our series, hypothyroidism was analyzed separately from the reelin variable due to published evidence, but there was only one case of hypothyroidism in the analyzed sample, and it was being treated." (PMID 34199942, 2021). "Hypothyroidism reduces reelin expression during neurodevelopment in early stages of noxa." (PMID 34199942, 2021).
ischemia (2 papers, 2011 to 2020). A hypoperfusion of the BLOOD through an organ or tissue caused by a PATHOLOGIC CONSTRICTION or obstruction of its BLOOD VESSELS, or an absence of BLOOD CIRCULATION. "However, in the ischemia model, the highest number of cells with high Reelin expression was in close proximity to the infarct." (PMID 21647369, 2011).
metastatic tumor (2 papers, 2021). "In addition, comparing metastatic colorectal diseases with primary tumors, the expression of Reelin increased significantly in metastatic tumors." (PMID 34485127, 2021). "Previous studies have shown that Reelin expression is reduced in TNBC compared to hormone-positive breast cancer; TNBC primary and metastatic tumor samples express lower levels of Reelin compared to Her-2 positive tumors and metastases." (PMID 33477804, 2021).
Obesity (2 papers, 2016 to 2020). Accumulation of substantial excess body fat. "As extraversion is known to be associated with lifestyle, obesity and substance abuse, we deem BDNF to be an interesting candidate gene for extraversion in future studies, along with CRTAC, ADAM12 and RELN." (PMID 26362575, 2016).
retinoblastoma (2 papers, 2011 to 2025). A malignant tumor that originates in the nuclear layer of the retina. "Treatment of retinoblastoma cell line RB522A with Reelin resulted in increased tyrosine phosphorylation of Dab1." (PMID 22163036, 2011).
spinocerebellar ataxia type 37 (2 papers, 2021 to 2023). Spinocerebellar ataxia type 37 (SCA37) is a subtype of autosomal dominant cerebellar ataxia type 1 (ADCA type 1), characterized by a cerebellar syndrome along with altered vertical eye movements. "Reelin signaling dysregulation was also observed in the cerebellum of patients with SCA37 (spinocerebellar ataxia type 37) and was attributed to a mutation in the Dab1 chromosomal region." (PMID 37891846, 2023). "DAB1 gene [also known as spinocerebellar ataxia type 37 (SCA37)] located on 1p32.2 consists of 21 exons and encodes the adaptor protein reelin." (PMID 34707478, 2021).
tuberous sclerosis (2 papers, 2022 to 2025). Hereditary disease characterized by seizures, intellectual disability, developmental delay, and skin and ocular lesions. "Impaired Reelin signaling due to constitutive activation of the mTORC1 pathway plays an important role in abnormal neuronal migration in tuberous sclerosis complex (TSC) pathology." (PMID 35668055, 2022).
ZIKV infection (2 papers, 2018 to 2023).
Anosmia (1 paper, 2016). An inability to perceive odors. "In conclusion, we complement the discovery by others that PLD2KO mice are resistant to Alzheimer’s insult by showing that these mice also suffer from anosmia and subtle cytoarchitectural abnormalities that may phenocopy mice with deficiency in the reelin pathway." (PMID 27658289, 2016).
Asperger Syndrome (1 paper, 2023). "The aim of this research was to analyze the methylation profile of four well-known genes involved in neurodevelopment (BDNF, RELN, MTHFR and HTR1A) in the mothers of forty-five age-matched AS (Asperger Syndrome), ADHD (Attention Deficit Hyperactivity Disorder) and typically developing children." (PMID 36980856, 2023).
ataxia telangiectasia (1 paper, 2023). Ataxia-telangiectasia is the association of severe combined immunodeficiency (affecting mainly the humoral immune response) with progressive cerebellar ataxia. "In addition, decreased levels of Reelin, together with early deficits in Reelin signaling, have been evidenced in the cerebrospinal fluid of patients with Ataxia-telangiectasia (A-T), and a decreased expression of the Reelin receptor was shown in a mouse model of A-T (Atm-/-)." (PMID 37891846, 2023).
bladder carcinomas (1 paper, 2024). "SW780 is a grade I carcinoma cell line, which means that RELN could become a pre-diagnosis for bladder carcinomas." (PMID 38307969, 2024).
Breast Invasive Carcinoma (1 paper, 2021). "Our bioinformatic analysis using the Breast Invasive Carcinoma dataset in cBioPortal, further reveals that RELN mRNA expression is reduced in basal-type tumor samples compared to normal tissue samples." (PMID 33477804, 2021). "Consistently, we performed bioinformatic analysis of patient data using cBioPortal (Breast Invasive Carcinoma dataset, TCGA, PanCancer Atlas) to show that RELN mRNA is reduced in basal-like subtypes (generally considered triple-negative) compared to normal samples." (PMID 33477804, 2021).
cardiomyopathy (1 paper, 2017). A disease of the heart muscle or myocardium proper. "A small number of other genes were regulated inversely in different adult forms of cardiomyopathy (RCM/DCM or RCM/ICM datasets) relative to RCM, including intelectin 1 (ITLN1), delta-like 1 homolog (DLK1), reelin (RELN), and myosin light chain kinase family, member 4 (MYLK4)." (PMID 28098235, 2017).
cocaine dependence (1 paper, 2012). A psychologically and socially impaired state, with or without physiological changes, that develops as a result of using cocaine and which leads to compulsive behaviors to acquire the substance. "Furthermore, four other genes, FAM38B (cocaine dependence in black women), PTPRM (marijuana dependence in black women), CSMD1 (nicotine dependence in black women), and RELN (cocaine dependence in white men), contain at least one SNP that met the SNP-based relaxed threshold of significance." (PMID 23365539, 2012).
colon adenocarcinoma (1 paper, 2022). "These reelin changes were the opposite of those in DNMT-1 expression and activity, which, via the hypomethylation of the reelin promoter in acute colitis and hypermethylation in colon adenocarcinoma, increases or represses reelin expression, respectively." (PMID 36290310, 2022). "Since we previously reported, reelin downregulation in human colon adenocarcinoma together with upregulation of both DNMT-1 and ApoER2, we next examined how these genes behave in each type of colon lesion." (PMID 36290310, 2022). "We previously reported that ApoER2 appears to negatively regulate reelin expression in human colon adenocarcinoma." (PMID 36290310, 2022). "Reelin expression was higher in the tissue adjacent to the colon adenocarcinoma and lower in the lesion itself." (PMID 36290310, 2022).
colon polyps (1 paper, 2022). "We considered of interest to find out whether the tissue surrounding (adjacent to) the colon polyp and adenocarcinoma exhibits changes in reelin, DNMT-1 and ApoER2 mRNA expression." (PMID 36290310, 2022). "The relative abundances of reelin, DNMT-1 and ApoER2 mRNAs were determined by PCR in the colon samples cited above and in the tissue adjacent to mouse colon polyps and adenocarcinomas." (PMID 36290310, 2022).
Crohn disease (1 paper, 2025). A gastrointestinal disorder characterized by chronic inflammation involving all layers of the intestinal wall, noncaseating granulomas affecting the intestinal wall and regional lymph nodes, and transmural fibrosis. "Canonical Reelin signaling also appears to be active in the homeostasis of the intestine and colon, suggesting also Reelin’s potential influence in the pathophysiology of some life-threatening chronic and inflammatory syndromes such as Crohn’s Disease." (PMID 40806482, 2025).
demyelination (1 paper, 2011). "To assess the extent to which Reelin-induced NSPC dispersion and migration is functionally beneficial to enhance spontaneous repair processes, we induced a focal demyelination lesion by lysolecithin injection in the corpus callosum of Wt and TgRln animals." (PMID 21647369, 2011). "Altogether these results led us to propose that the endogenous up-regulation of Reelin after a lesion facilitates the exit of SVZ-derived progenitors from the RMS and thereby promotes their recruitment toward a demyelination lesion in the adult brain." (PMID 21647369, 2011). "Here, we uncover a new role for Reelin in post-lesional cell migration in the adult brain and provide proof of concept that allowing cells to escape from the RMS promotes endogenous cell replacement at the lesion site in a mouse model of demyelination." (PMID 21647369, 2011).
diffuse large B-cell lymphoma (1 paper, 2023). "The result showed 23 gene mutations, including MYD88, CD79B, CDKN2A, PIM1, RELN, PCLO, CREBBP, and so on, supporting the diagnosis of diffuse large B-cell lymphoma." (PMID 36599976, 2023). "The genetic test results of the left frontal parietal lobe lesion result revealed 23 gene mutations, including MYD88, CD79B, CDKN2A, PIM1, RELN, PCLO, CREBBP, and so on, supporting the diagnosis of diffuse large B-cell lymphoma." (PMID 36599976, 2023).
Dysequilibrium syndrome (1 paper, 2013). "We identified a novel mutation, p.Asp487Tyr, in the VLDLR gene involved in the Reelin developmental pathway and associated with a rare form of LCH, the Dysequilibrium Syndrome." (PMID 24498604, 2013).
dysplastic nevi (1 paper, 2017). "We investigated reelin presence in 32 melanocytic nevi (5 junctional, 27 compound or 14 dysplastic nevi and 18 non dysplastic nevi)." (PMID 28255385, 2017). "Non-dysplastic nevi stained intensely positive for reelin in 16% of the cases (3/ 18), moderately positive in 16% of the cases (3/ 18), and weakly positive or negative in 50% of the cases (9/ 18 and 3/ 18, respectively)." (PMID 28255385, 2017). "The presence of reelin was elevated in junctional areas as in dysplastic nevi." (PMID 28255385, 2017). "The presence of reelin could not be correlated with the clinical appearance of nevi undergoing excision in non-dysplastic nevi." (PMID 28255385, 2017).
endothelial dysfunction (1 paper, 2023). In vascular diseases, endothelial dysfunction is a systemic pathological state of the endothelium (the inner lining of blood vessels) and can be broadly defined as an imbalance between vasodilating and vasoconstricting substances produced by (or acting on) the endothelium. "We have previously identified a circulating protein, Reelin, that is central in the initiation and propagation of endothelial dysfunction with additional prothrombotic function." (PMID 37441066, 2023). "However, it appears that endothelial dysfunction and inflammation no longer persist in long COVID, as the levels of Reelin and inflammatory mediators in these PACS patients are not different from controls." (PMID 37441066, 2023).
ependymoma (1 paper, 2016). A WHO grade II, slow growing tumor of children and young adults, usually located intraventricularly. "Poor prognostic features were found in two other patients: low expression of PAX8, FHIT, CASP10, CHD2, with high expression of CHD11, FUS, and MTA1 in a patient with Ewing sarcoma, and gain of 1q and loss of 6q and overexpression of TNC, CALB1, PLAG1, ALDH1L1, and RELN in a patient with ependymoma." (PMID 28007021, 2016).
epileptic seizures (1 paper, 2019). "Interestingly, the incubation of neurons with kainic acid, as an in vitro model for epileptic seizures, leads to GC dispersion and decreased proteolytic processing of Reelin evidenced by an increase in the full length 400 kDa protein and a decrease in the 320 kDa secreted Reelin." (PMID 31134199, 2019).
epithelial ovarian cancer (1 paper, 2023). "We found that the loss of CTGF in epithelial ovarian cancer cells is associated with modifications on the expression of several genes associated with the ECM, including LAMC2 SPP1, SV2A, RELN, COL6A3, and COL4A6." (PMID 37835529, 2023).
experimental autoimmune encephalomyelitis (1 paper, 2024). An autoimmune demyelinating disease of the central nervous system that is produced experimentally in animals by the injection of homogenized brain or spinal cord in Freund's adjuvant. "First, to test if the anti-Reelin antibody CR-50 interferes with CNS Reelin, we have challenged the BBB and increased its permeability using the experimental autoimmune encephalomyelitis (EAE) mouse model." (PMID 38607022, 2024). "Furthermore, in mice induced with experimental autoimmune encephalomyelitis (EAE), selective modulation of endothelial responses by anti-Reelin antibodies reduces pathological leukocyte infiltration without completely abolishing diapedesis." (PMID 38607022, 2024).
fetal growth restriction (1 paper, 2021). A fetus that does not grow beyond the 10th percentile of conventionally accepted weight for gestational age. "Our objective is to analyze whether there is an association of reelin serum levels in cord blood of NBs with fetal growth restriction and its different growth restriction stages." (PMID 34199942, 2021). "The purpose of this article is to study whether reelin levels in new-borns vary as a function of severity of fetal growth restriction by gestational age and sex." (PMID 34199942, 2021).
Focal cortical dysplasia (1 paper, 2022). A type of malformation of cortical development that primarily affects areas of neocortex. "In a subtype of focal cortical dysplasia (FCD) in which abnormal cortical layering occurs in association with HS and GCD, loss of reelin has been identified as the pathogenetic basis, arguing for a link between reduced reelin expression and GCD in humans." (PMID 35733853, 2022).
focal epilepsy (1 paper, 2024). A seizure caused by a localized disorder. "As noted, proteolytic processing of Reelin is critical for the maintenance of granule cell lamination in the DG and the regulation of the GCD in the model of TLE, a chronic form of focal epilepsy that is often associated with SRS and characteristic hippocampal sclerosis." (PMID 38540798, 2024).
fragile X syndrome (1 paper, 2018). A genetic syndrome caused by mutations in the FMR1 gene which is responsible for the expression of the fragile X mental retardation 1 protein. "Besides high penetrance monogenic disorders like Fragile X Syndrome, prominent genes that have been identified include Reelin (RELN), MET, serotonin transporter (5HTT) and engrailed 2 (EN2)." (PMID 29691724, 2018).
head and neck squamous cell carcinoma (1 paper, 2021). A squamous cell carcinoma that arises from any of the following anatomic sites: lip and oral cavity, nasal cavity, paranasal sinuses, pharynx, larynx, and salivary glands. "The relationship between Reelin and tumor immune microenvironment in head and neck squamous cell carcinoma (HNSCC) tissues was determined by TISIDB and the Tumor Immune Estimation Resource (TIMER) database." (PMID 34485127, 2021).
injury (1 paper, 2011). Damage inflicted on the body as the direct or indirect result of an external force, with or without disruption of structural continuity. "Our data shed new light on a previous study reporting increased susceptibility of Reelin-deficient mice to ichemic brain injury." (PMID 21647369, 2011).
Insulin resistance (1 paper, 2017). Increased resistance towards insulin, that is, diminished effectiveness of insulin in reducing blood glucose levels. "PI3Ks also modulate glucose uptake and storage in the brain through the Reelin Signaling in Neurons pathway (network 1) which has been shown to affect feeding behaviors and promote insulin resistance." (PMID 29326659, 2017).
Intraventricular hemorrhage (1 paper, 2021). Bleeding into the ventricles of the brain. "The two NBs with intraventricular hemorrhage (IVH) had reelin levels three times lower than the rest of the NBs analyzed." (PMID 34199942, 2021).
ischemic stroke (1 paper, 2022). A stroke disorder caused by obstruction of blood flow to the brain, due to thrombotic (local blood clot formation) or embolic (due to a blood clot or other material traveling from another site) event. "Here, we examined the ability of PLGA‐PEG micelles loaded with Reelin in the modulation of mouse NSCs dynamic growths, differentiation, neurite growth, and neuroregenerative potential in in vitro condition and in vivo ischemic stroke model." (PMID 35111956, 2022). "Taken together, our study presents eligibility and suitability of Reelin‐loaded PLGA‐PEG micelles on neural tissue regeneration and functional recovery following ischemic stroke, leading to the introduction of novel approaches in the field of neural tissue engineering and regenerative medicine." (PMID 35111956, 2022).
kidney cancer (1 paper, 2016). Primary or metastatic malignant neoplasm involving the kidney. "qRT-PCR was performed on all six cell lines for the three candidate genes (RELN, FOXC2, and CLIP4) to identify those with significant fold-changes in gene expression in the kidney cancer cell lines compared to the normal kidney cell line." (PMID 27283491, 2016).
Learning disabilities (1 paper, 2019). "For example, in a mouse model of genetically manipulated inhibition of the Reelin/LRP8 signaling pathway, mice demonstrated marked fear-conditioning deficits and Learning disabilities." (PMID 30622122, 2019).
lissencephaly type 1 (1 paper, 2025). "The impaired and disturbed cortical migration phenotype of the GB model is similar to the phenotype of the human disease lissencephaly type 1, which is characterized by reduction of Reelin, an important regulator of radial migration, mainly expressed by CR cells." (PMID 40680886, 2025).